IL6 (interleukin 6)
Diseases named in the same sentence as IL6 in open-access papers (continued):
Sharing a sentence is not in itself a finding about the gene and the disease.
breast cancer (continued). "Moreover, in a murine model of orthotopic 4T1 breast cancer, DOX-INH suppressed Shh, IL-6, and TGF-β signaling pathways and thus mitigated EMT and the growth and metastasis of breast cancer cells." (PMID 39714760, 2025). "IL-6 and TNF-alpha are emerging as prognostic biomarkers of poor survival in breast cancer." (PMID 40558287, 2025). "This is the first study to investigate not only the distinct and independent effects of different exercise modes on anti-cancer myokines such as decorin, IL-6, OSM, and SPARC in survivors of breast cancer, but also in exploring the effects of such exercise modes on MDA-MB-231 cell growth in vitro." (PMID 40608178, 2025). "TGF-β1/SMAD/HLF-activated IL-6 in TNBC cells induces a TAM-like phenotype via the JAK/STAT3 pathway and further upregulates TGF-β 1 expression, constituting a feedback circuit that promotes breast cancer ferroptosis resistance." (PMID 39858015, 2025). "Inclusion criteria were: intervention group receiving mind–body exercises such as mindfulness or yoga; control group receiving standard care; participants aged ≥18 years with breast cancer; and outcomes including anxiety, fear of cancer recurrence (FCR), fatigue, IL-6, and 7 other indicators." (PMID 41221238, 2025). "However, the potential of IL6 to induce and maintain EMT in breast cancer cell lines depends on activation of the JAK/STAT3 pathway." (PMID 40141419, 2025). "Preclinical evidence from related Vaccinium species suggests VAC's translational potential: V. macrocarpon (cranberry) reduced DMBA‐induced mammary tumors by 73% (tamoxifen 55%); V. myrtillus (bilberry) inhibited 4T1 lung metastasis by 82% in BALB/c mice through suppression of IL‐6/STAT3 signaling." (PMID 41234608, 2025). "In vitro studies have confirmed that TAMs can contribute to the development of endocrine resistance in estrogen receptor-positive (ER+) breast cancer cells by prolonging the release of TNF-α and interleukin 6 both by themselves and by the cancer cells they affect." (PMID 41301715, 2025). "Exercise has been shown to reduce IL-6 levels and enhance type I interferon production in breast cancer survivors, as recently confirmed in female breast cancer survivors, offering a non-pharmacologic avenue to shift the immune balance." (PMID 41007766, 2025). "In this regard, it is important to mention that ZEB1 has been shown as a direct transcriptional (co-)inducer of inflammatory gene expression, like IL6, IL8 and others in several cell types, such as breast cancer cells and fibroblasts, corneal fibroblasts, hematopoietic and myeloid cells." (PMID 38937629, 2024). "Our data showed that this compound reduced the expression of IL-6 mRNA and STAT3, which promote proliferation, metastasis, invasion, and angiogenesis in breast cancers, and could result in the suppression of the NF-kB/IL-6/JAK2/STAT3 signaling pathway." (PMID 38673967, 2024). "Notably, it has been observed that IL-6 stimulation can induce YBX1 expression, suggesting the existence of a positive feed-forward loop that contributes to the process of EMT in breast cancer cell lines." (PMID 38255791, 2024). "Interestingly, BZA exhibited preclinical efficacy against HR-breast cancer, which was later attributed to its ability to bind the D1 domain of the GP130 receptor and subsequently disrupt IL-6/IL-6R/GP130 signaling." (PMID 39768178, 2024). "IL-6 and IL-8 are involved in proinflammatory responses, angiogenesis, and stemness and are negative prognostic markers for breast cancer." (PMID 38314029, 2024). "Its supernatant could inhibit the autocrine secretion of IL-6 and the phosphorylation of JAK2/STAT3 in the breast cancer cell line MCF-758." (PMID 38395948, 2024). "Also, the invasion of MDA-MB-231 cells was enhanced by IL-6 (~3-fold); interestingly, the basal and induced invasion was inhibited by G15, highlighting the role of GPR30 in the cell invasion of breast cancer cells." (PMID 39201674, 2024).
breast cancer (continued). "While miR-146b-5p has not been studied in the TM, it also inhibited NF-κB-induced interleukin 6 (IL-6) expression in breast cancer cells." (PMID 38920689, 2024). "Collectively, our findings demonstrate that dual-targeting tGLI1 and IL-6/IL-6R/GP130 signaling pathways are effective against HER2-enriched breast cancer and TNBC and support the use of tGLI1 and IL-6/IL-6R/GP130 inhibitors for the treatment of these more aggressive subtypes of breast cancer." (PMID 39768178, 2024). "High tGAS+IL-6/IL-6R/GP130 activation did not significantly impact MFS in luminal breast cancer patients when compared to low tGAS+IL-6/IL-6R/GP130." (PMID 39768178, 2024). "In primary breast cancer, miR-146 expresses a negative feedback loop to IL-6 as a mean to inhibit the tumor progression initiated by IL-6/STAT3 pathway." (PMID 38726321, 2024). "Furthermore, the top upregulated pathway in aneuploid cB-ALL samples was IL6 JAK-STAT3 signaling (F and Dataset EV2), which has been recently involved in adaptation of breast cancer cells to CIN." (PMID 38177531, 2024). "Monocytes, as a type of inflammatory cells, not only secrete inflammatory factors such as IL-1, IL-6, IL-10, and TNF-α to promote tumor microangiogenesis, but also assist in the adhesion of tumor cells to endothelial cells, thereby promoting breast cancer metastasis." (PMID 38834662, 2024). "Concerning breast cancer, our previous data reported that SDC1 depletion in MDA-MB-231 cells increased cell adhesion and migration on fibronectin, but the addition of exogenous IL-6 suppressed this migratory behavior." (PMID 36980680, 2023). "Moreover, the percentage of breast cancer cells expressing CD44high/CD24low, as well as the protein and transcript levels of signal transducer and activator of transcription 3 (STAT3) and IL-6, are reduced by catechol treatment." (PMID 36902427, 2023). "When the IL-6 levels were compared between the SKBR3 and HCC1954 cells, representative breast cancer cell lines that are sensitive and resistant to TRZ, respectively, IL-6 expression was significantly higher in the HCC1954 cells compared to those of the SKBR3 cells." (PMID 36979654, 2023). "Nevertheless, similar to our results presented here for colorectal cancer, we found that key genes of major cell-signaling cascades that drive tumorigenesis, e.g., JAK STAT (IL6), Src, RTK (EGFR), PI3K, and MAPK, were also highly correlated with the expression of inflammatory genes in breast cancer." (PMID 37190308, 2023). "Moreover, breast cancer patients with adipose inflammation have increased insulin, glucose, leptin, triglycerides, CRP, and IL-6 levels as well as decreased HDL and adiponectin levels." (PMID 36670988, 2023). "In the present study, IL6, IL8, and MMP3, which have been highlighted for their pro‐tumorigenic activities of individual SASP factors in many studies, produced by LAP‐induced senescent breast cancer cells." (PMID 37792675, 2023). "Finally, the activation of mGluR1 in MDA-MB-231 breast cancer cells can release the cytokines and chemokines (CXCL1, IL6, IL8) that activate the immune-suppressive immune cell promoting the malignant transformation of breast cancer cells." (PMID 36817470, 2023). "Thus, inhibiting the inflammatory mediators (IL-6, G-CSF) or downstream MEK signaling prevented chemotherapy (DTX)-induced breast cancer dormancy awakening and ameliorated a potentially tumor immunosuppressive microenvironment." (PMID 37699010, 2023). "Whereas, breast cancer cells exposed to RT alone displayed an augmentation in TGF-β, VEGF, INF-γ, IL-2, and IL-6 levels by 31, 45.5, 36.5, 51, and 88.6%, respectively, for MCF-7 cells, and by 27.1, 28.5, 68.6, 136, and 124.2%, respectively, for MDA cells when compared with Amy-F group." (PMID 37210478, 2023). "A previous study showed the high production of pro-inflammatory cytokine IL-6 in highly invasive breast cancer cell line MDA-MB-231, but not in low invasive breast cancer cell line MCF-7." (PMID 37501379, 2023).
breast cancer (continued). "Anti-IL-6 treatment alone prolonged the survival time but did not improve the survival rate of the 4T1 breast cancer-bearing mice." (PMID 37108179, 2023). "In socially isolated animals, the herbal product inhibited IL6/JAK/STAT3 signaling, upregulated OXPHOS signaling, suppressed the expression of RAGE ligands S100a8 and S100a9, and prevented the increase in recurrence of dormant mammary tumors." (PMID 36980301, 2023). "Impaired IL-6 signaling has been detected in peripheral T cells from both non-small cell lung cancer (NSCLC) patients with high vs low plasma IL-6 concentrations, and in breast cancer patients compared to healthy donors." (PMID 37741983, 2023). "We also determined the changes in the IL6 and STAT3 levels in mammary tumors." (PMID 36980301, 2023). "Importantly, HDAC4-related inhibitors can inhibit the activation of downstream IL-6/STAT3 signaling to suppress the growth and metastasis of breast cancer." (PMID 37843550, 2023). "We demonstrated that the fragmented PPMPs promoted the cell cycle, proliferation, and secretion of the inflammatory cytokine IL-6 in human breast cancer cells, while PPMPs did not induce cytotoxicity nor enhance cellular motility." (PMID 37069244, 2023). "CAFs secrete interleukin 6 (IL-6) which activates signal transducer and activator of transcription 3 (STAT3) signaling pathway, thus promoting the growth and radioresistance of breast cancer cells." (PMID 36635302, 2023). "Basic research has shown that IL-6 and TGF-β closely interact with each other in the breast cancer microenvironment, so both of these mediators may be associated with prognosis in patients receiving eribulin." (PMID 37733188, 2023). "This study revealed the non-canonical molecular mechanism of IL-6 secreted by breast cancer upregulated KDM2A expression in CAFs via a novel STAT3/NFκB p50 axis, which STAT3 complexed with NFκB p50 in NFκB p50 binding motif of KDM2A promoter." (PMID 37821959, 2023). "An important regulator of EMT in breast cancer is IL-6; it is highly expressed in adipocytes and is abundant in normal breast tissue." (PMID 36831154, 2023). "IL-17 can also induce the production of IL-6 and CCL20 in metastatic, but not in non-metastatic breast cancer tumor cells, thereby promoting inflammation and proliferation through IL-6 mediated STAT3 pathway activation." (PMID 37427128, 2023). "For instance, it was demonstrated that CCL2/monocyte chemoattractant protein-1, CCL5, IL-1β, IL-6, tumor necrosis factor α, vascular endothelial growth factor, and leptin released by CAAs in the TME promote the proliferation, and dissemination of breast cancer cells." (PMID 36980280, 2023). "In addition, IL-6, VEGF and NF-κB promotes the expression of c-MYC via STAT3, leading to the development of breast cancer invasion and metastasis." (PMID 36721232, 2023). "Higher IL-6 levels are observed in breast cancer patients with the − 174 G/G genotype, ER negative tumors and bone metastasis." (PMID 36693957, 2023). "Overall, IL6 showed a significant role in the HSPB1-mediated malignant behaviors, and it is possible that HSPB1 is involved in the regulatory function of IL6 through modulating NF-κB activity in breast cancer." (PMID 37454220, 2023). "However, the interplay between breast cancer cells and fibroblasts, as well as the modes of action of TGF-β, PDGF, and IL-6, are difficult to investigate in vivo." (PMID 37173963, 2023). "For instance, it has been demonstrated that IL-6, secreted by adipocytes, is able to induce epithelial–mesenchymal transition, enrichment of cancer stem cells, and resistance to PI3K inhibitors via STAT3 activation in ER-expressing MCF-7 breast cancer cells." (PMID 37834225, 2023). "For instance, cytokines like IL-1β, IL-6, IL-8, and TNF-α play a crucial role in breast cancer." (PMID 37569777, 2023).
breast cancer (continued). "Although the FDA has not approved any IL-6/JAK/STAT3 pathway inhibitors for breast cancer, many of them are currently under development in preclinical and clinical investigation." (PMID 37237509, 2023). "Furthermore, clinical analyses were conducted for the sera samples of prostate and breast cancer patients for CRP, cytokines levels (IFN-γ, TNF-α and IL-6), and oxidative stress level markers (MDA and carbonyl contents)." (PMID 37153524, 2023). "It has been reported that TAMs promote the resistance of breast cancer cells to paclitaxel by inhibiting the activation of CD8 + T lymphocytes, and TAMs can also promote the chemoresistance of colorectal cells by secreting IL-6." (PMID 36641471, 2023). "Co-culturing lung fibroblasts with human breast cancer increased the secretion of CXCL1 and IL-6." (PMID 36607556, 2023). "Lunasin did not affect normal MCF-10A cell growth but inhibited breast cancer cell growth, increased interleukin (IL)-6 gene expression and protein production at 24 h, and decreased its secretion at 48 h." (PMID 36794014, 2023). "Consistently, IL-6, LIF, and STAT3 were found to regulate breast cancer dormancy in the bone." (PMID 37440925, 2023). "We have previously shown that SDC1 expression affects cancer stem cell-related pathway components, including IL-6/STAT3, Notch, and EGFR signaling pathways, in SUM-149 triple-negative inflammatory breast cancer cells, an aggressive and deadly form of breast cancer." (PMID 36980680, 2023). "Tumors from humanized breast cancer models exhibited high levels of GMCSF, IL-6, IL-8, and TNFα." (PMID 36860657, 2023). "Inhibition of cathepsin K may inhibit breast cancer bone metastasis by reducing the expressions of TNF-α, IL-6, and IL-1β." (PMID 37398678, 2023). "These “educated” osteoblasts express RUNX2/osteocalcin (OCN)/OPN, are negative for IL-6 and α-smooth muscle actin (αSMA), and have new properties where they acquire the capacity to suppress both triple-negative and ER+ breast cancer cell proliferation." (PMID 37296983, 2023). "TRPV1 activation in tumor-bearing mice (breast carcinoma) decreases IFN-γ and increases IL-6." (PMID 37371563, 2023). "In addition, in the breast cancer surgery group, postoperative VEGF levels were lower (P < 0.05) and IL-6 levels were higher (P < 0.05) compared to preoperative levels." (PMID 36531035, 2022). "For breast cancer cells, IL-6/JAK/Stat3 signaling pathway is essential to maintain the CSCs property (CD44+CD24− cells), which suggested a prospective therapy mean to target the stem-like breast cancer cells." (PMID 36678534, 2022). "Therefore, it remains pertinent to maintain a homeostatic balance of IL-6/JAK/STAT3 as dysregulation creates a vicious autocrine and paracrine inflammatory loop which promotes breast cancer metastasis and therapeutic resistance." (PMID 35371975, 2022). "Of note, when breast cancer cells were co-cultured with osteoclasts, increased levels of IL-6, IL-8, MCP-1 and macrophage inflammatory protein 1α (MIP-1α) were observed in the breast cancer compartment, which point to an effect of osteoclasts on MDA-1833 secretome." (PMID 35243294, 2022). "Pentadecanoic acid suppresses the CSC subpopulation through inhibition of IL-6/JAK/STAT3 signaling and increases apoptosis in ER+ breast cancer cell line; however, the exact mechanism remains unknown." (PMID 35371975, 2022). "In an RCT involving early-stage breast cancer patients, 8 weeks of MBSR promoted significantly better NK cell activity and lower levels of TNFα, IL-6, and interferon gamma (IFNγ) compared to the control group, who participated in a series of cancer recovery and health education classes (n = 124)." (PMID 35682203, 2022). "In line with the last hypothesis, eliminating the NF‐κB‐dependent pro‐inflammatory SASP, including IL6 and IL8, was sufficient to abolish SASP‐induced NED in breast cancer cells." (PMID 35653631, 2022).
breast cancer (continued). "To further confirm the selectivity of LLL12B in breast cancer cells, we tested its effects on the phosphorylation of STAT3, STAT1, or ERK following the stimulation with IL-6, IFN-γ, or EGF in the T47D breast cancer cells, which express lower basal levels of P-STAT3, and in the MDA-MB-231 TNBC cells." (PMID 36009550, 2022). "Serum IL-5, IL-6, IL-8, IL-17, VEGF levels and lymph node metastasis in breast cancer patients." (PMID 36531035, 2022). "In addition, STAT3 was reported to be activated by inflammatory cytokines, such as IL6, IL8 and TNFα, which enhance breast cancer proliferation, invasion and metastasis through the upregulation of Twist, Snail, Slug, Vimentin and HIF-1α." (PMID 35747796, 2022). "IL-6 has been identified as a cytokine abundantly present in the TME of various tumour types, including head and neck squamous cell carcinoma (HNSCC), pancreatic cancer, non-small-cell lung cancer, breast cancer, ovarian cancer, and melanoma." (PMID 36429126, 2022). "Furthermore, adipocyte-derived IL-6 promotes the spheroid formation of BCSCs by stimulating NF-κB and STAT3 signaling pathways in HER2-positive breast cancer." (PMID 35805056, 2022). "WA is a herbal which promises the inhibition ofapoptosis in human breast cancer cells by mediating mitochondria as shown by Hahm (2011) and can inhibit the cell migration even after the activation of STAT3 by Interleukin-6(IL-6), which is a beneficial effect ofWA as shown by Lee (2010)." (PMID 37426503, 2022). "Statins have also been demonstrated in vitro to decrease interleukin-6 (IL6) production in breast cancer cell lines and non-breast cancer cell lines." (PMID 35433431, 2022). "Also, high levels of adipocytes lead to up-regulated IL6, which build resistance to anti-VEGF therapy in breast cancer." (PMID 35294447, 2022). "In addition to IL-6, TGF-b1 and IL-1b have been found to enhance the expression and secretion levels of OPG in mouse stromal cells and breast cancer cell lines, respectively." (PMID 36359766, 2022). "In addition, elevated serum concentrations of IL-6, IL-10, IL-1β, and TNF-α are found in a variety of cancer types, including breast cancer." (PMID 36482346, 2022). "In our analysis of HER2, IL-6, and pSTAT3 levels in a panel of primary IBCs, we found substantial co-localization of HER2 and pSTAT3, consistent with pSTAT3 as a known key regulator of growth in HER2pos breast cancer cells." (PMID 35565421, 2022). "It has been shown that breast cancer cell-derived sEVs enhance TAM expression of IL-1β, IL-6, and TNF-αand that TANs inhibit 4T1-cell sEV secretion, resulting in a marked decrease in IL-1β, IL-6, and TNF-α." (PMID 36096820, 2022). "Indeed, over half of all primary human breast cancers and corresponding breast cancer cell lines show prominent accumulation of the activated form of the STAT3 transcription factor engaged by IL-6 signaling, suggesting widespread involvement of this pathway." (PMID 35565421, 2022). "In CSCs, the IL-6/gp130/STAT3 signaling pathway has been demonstrated to be involved in the regulation of CSC properties such as self-renewal, stemness marker expression, and tumor cell growth in prostate cancer, glioma, endometrial cancer, and breast cancer." (PMID 35565185, 2022). "In breast tumor cells, it has been identified that MSCs could be selectively recruited to the sites of growing carcinoma through cytokine such as IL-6 and CXCL7, where they interact with breast cancer CSCs." (PMID 35924148, 2022). "Therefore, with the approval of immunotherapy for this subtype, it is worth considering the mechanistic link found between IL-6 and PDL1 to be applied in breast cancer treatment." (PMID 35163731, 2022). "An in vitro study showed that IL-6 and IL-8 in senescence-conditioned medium (SCM) from senescent foreskin fibroblasts, HCA2, can increase the expression of vimentin, ZEB-1, SNAIL-1, and SNAIL-2/Slug in MCF-7 breast cancer cells." (PMID 36291773, 2022).